ABO (ABO, alpha 1-3-N-acetylgalactosaminyltransferase and alpha 1-3-galactosyltransferase)
Diseases named in the same sentence as ABO in open-access papers (continued):
Sharing a sentence is not in itself a finding about the gene and the disease.
genetic disorders (1 paper, 2012). "Hence, single nucleotide substitution of the cis-element in pre-mRNA splicing machinery not only associate with the development of various diseases and genetic disorders, but also accounts for the genetic changes associated with ABO blood subtypes." (PMID 22624005, 2012).
musculoskeletal diseases (1 paper, 2023). "In conclusion, we found the ABO/RhD blood groups to be associated with a wide spectrum of diseases, including cardiovascular-, infectious-, gastrointestinal- and musculoskeletal diseases." (PMID 36892462, 2023).
ABO also shares sentences with these, for which no sentence is quoted: Alzheimer disease (5 papers); Hypertension (4); metabolic disease (4); acute myocardial infarction (3); Graves disease (3); heart disease (3); hyperlipidemia (3); non-small cell lung carcinoma (3); pernicious anemia (3); pulmonary heart disease (3); rheumatoid arthritis (3); stomach cancer (3); acute leukemia (2); atrophic gastritis (2); autoimmune disease (2); chronic hepatitis (2); coronary atherosclerosis (2); dementia (2); Diarrhea (2); endothelial dysfunction (2); gastritis (2); gastrointestinal disease (2); haemophilia A (2); hemoglobinopathies (2); inflammatory bowel disease (2); nasopharyngeal carcinoma (2); neurologic diseases (2); pulmonary embolism (2); schistosomiasis (2); squamous cell carcinoma (2).
A further 106 diseases each share a sentence with ABO in 2 papers or fewer.